MIF (macrophage migration inhibitory factor)
Diseases named in the same sentence as MIF in open-access papers (continued):
Sharing a sentence is not in itself a finding about the gene and the disease.
anemia (continued). "These molecules contribute to infection-induced anemia, as Gal-3 induce erythrophagocytosis, while MIF promotes the production of pro-inflammatory cytokines, including TNF." (PMID 36420267, 2022). "The Macrophage-mediated innate immune response controls parasite growth and anemia during acute Py17XL infection, while macrophage proinflammatory secretion is upregulated by MIF." (PMID 36093199, 2022). "As documented above, MIF plays an important role in the development of immunopathologies during experimental African trypanosome infection, including anaemia and liver injury." (PMID 35464430, 2022). "Since inflammatory cytokines play a key role in anemia development and since MIF can be an initiator of inflammatory cytokine production, we also evaluated the systemic levels of various pro-inflammatory cytokines." (PMID 32012211, 2020). "Collectively, during the chronic stage of T. congolense infection, MIF partially impaired recovery from early stage anemia and contributed to the decline in serum hemoglobin and iron levels." (PMID 27632207, 2016). "Based on the observation that MIF was produced in the chronic phase of T. congolense infection, we hypothesized that this less virulent model of African trypanosomosis could allow a refined analysis of the MIF-dependent pathogenic mechanisms at play during infection-induced tissue damage and anemia." (PMID 27632207, 2016). "We have recently reported that MIF, an upstream regulator of the inflammatory response, contributed to anemia in trypanosusceptible T. b. brucei-infected C57Bl/6 mice." (PMID 27632207, 2016). "More specifically, the effect of MIF on the infiltration of myeloid cells, liver damage and anemia development was investigated." (PMID 25255103, 2014). "Our data suggest that MIF promotes the most prominent pathological features of experimental trypanosome infections (i.e. anemia and liver injury), and prompt considering MIF as a novel target for treatment of trypanosomiasis-associated immunopathogenicity." (PMID 25255103, 2014). "MIF also promoted anemia development by suppressing red blood cell production and enhancing their clearance." (PMID 25255103, 2014). "MIF was shown to exacerbate immunopathology in P. yoelii 17XL infection as knockout mice displayed reduced parasitemia, delayed mortality, and less severe anaemia and cachexia." (PMID 41461395, 2026). "Here, the reduced anemia could be associated with the high serum levels of IL-10, and IL-12 and the deficiency of TNF-α, IFN-γ and MIF." (PMID 36093199, 2022). "Taken together, these data indicate that MIF deficiency delayed the development of cachexia and reduced early anemia and suggest that mortality does not seem to be fully related to weight loss." (PMID 36093199, 2022). "In addition, MIF importantly contributed to anemia development by (i) promoting iron accumulation in liver myeloid cells, (ii) enhancing RBC clearance, and (iii) suppressing erythropoiesis at later stages of erythroblast differentiation." (PMID 29497418, 2018). "However, infection of MIF knockout mice with P. chabaudi resulted in less severe anemia, improved erythroid progenitor development, and increased survival compared with wild-type controls." (PMID 27034825, 2016). "In contrast, anemia induced by T. congolense mainly occurred through MIF-dependent hemodilution." (PMID 27632207, 2016). "Moreover, a GPI-based intervention strategy was found to alleviate trypanosomosis-associated anemia development by lowering the proinflammatory cytokine production (including TNF, MIF, and Gal-3) and increasing IL-10 production." (PMID 26090446, 2015). "In this context, MIF might again be an important player as it was shown previously to be a driving force in suppressing erythropoiesis and promoting hemodilution leading to the observed “apparent” anemia during T. congolense infection." (PMID 32012211, 2020).
anemia (continued). "Finally, IL-12 and MIF have also been implicated in the pathophysiology of anemia but we did not observe a significant increase in IL-12, nor did we measure levels of MIF." (PMID 32373101, 2020). "In animal models, pro-inflammatory cytokines such as tumour necrosis factor (TNF), interleukin-12 (IL-12), macrophage migration inhibitory factor (MIF) have been shown to lead to dyserythropoiesis, which subsequently results in anaemia." (PMID 37710279, 2023). "Collectively, blocking MIF in TgAlbCre-IL10-/- mice, using an anti-MIF Nb, was found to attenuate anemia and excessive systemic inflammatory cytokine levels, without affecting parasite burden." (PMID 32012211, 2020). "A comparative gene expression analysis between M1 and M2 cells identified galectin-3 (Gal-3) and macrophage migration inhibitory factor (MIF) as novel M1-promoting factors, possibly acting synergistically and in concert with TNF-α during anemia development." (PMID 29497418, 2018). "Given that hemolysis was shown to occur during T. congolense infections, the increased levels of MIF observed during both the acute and chronic stage might mainly be due to parasite-inflicted rather that host-mediated damage of RBCs, which could also fuel a chronic (low-grade) anemia profile." (PMID 29497418, 2018). "In the absence of MIF, an increased maturation of reticulocytes to mature RBCs occurred and coincided with reduced splenomegaly and anemia." (PMID 27632207, 2016). "Together, these data indicated that anemia resulted from MIF-dependent hemodilution and not from lower production of RBCs in T. congolense-infected mice." (PMID 27632207, 2016). "These rMIF treatment data further support the conclusion that MIF exerted negative effects on anemia and hemodilution development during the later stage of T. congolense infection." (PMID 27632207, 2016).
Autoimmunity (24 papers, 2010 to 2025). The occurrence of an immune reaction against the organism's own cells or tissues. "The MIF gene encodes Macrophage Migration Inhibitory Factor (MIF) which serves as a proinflammatory factor that participates in autoimmunity in response to pathogens." (PMID 35844731, 2022). "The hypothesis that MIF rs755622 polymorphisms regulate MIF levels only in certain conditions, e.g., in response to infection, trauma, or autoimmunity, was confirmed in a cardiopulmonary bypass study." (PMID 32560699, 2020). "In addition to IL-8 and TNFα, we quantified levels of MIF, a protean pro-inflammatory mediator whose expression is increased in patients with RA and has been associated with severity of several autoimmune conditions." (PMID 20596538, 2010). "Elevated and detrimental MIF levels are secreted later, in response to chronic ongoing Ov infection and autoimmunity in NS patients and contribute to the perpetuation and severity of the infection, inflammation and/or autoimmunity." (PMID 34662363, 2021). "MIF is an immune-regulatory cytokine that is involved in numerous pathologies, which vary from infectious diseases, autoimmunity to neurodegenerative diseases." (PMID 34662363, 2021). "Evidence for a role for MIF in autoimmunity has been provided by studies showing that MIF is expressed at increasing levels in different experimental models of disease." (PMID 29915588, 2018). "Neither autoantibody production nor T and B cell activation was significantly affected, suggesting that the protective effect of MIF inhibition in SLE is dependent on the regulation of innate inflammation rather that autoimmunity." (PMID 26617609, 2015). "MIF is a pleiotropic protein that functions as a glucocorticoid-induced immunoregulator, pituitary hormone, inflammatory cytokine, and immune and growth response regulator, with pathologic roles in autoimmunity, neurologic disorders, and oncology." (PMID 38178143, 2024). "We demonstrate that CD8+ T effector memory cells might drive and sustain autoimmunity via macrophage migration inhibitory factor (MIF)‐CD74 signaling to immature B cells and CC‐chemokine ligand 5 (CCL5)‐mediated recruitment of cytotoxic CD4+ T cells." (PMID 34254741, 2021). "The data presented here suggest that IL-16 and MIF are neutrophil-derived inflammatory mediators released under conditions of insufficient clearance of apoptotic neutrophils, as typically occurs at sites of infection and autoimmunity." (PMID 27551482, 2015). "However, in affected patients, with established NS, MIF plasma levels are elevated compared to control subjects and might be involved with autoimmunity and neuroinflammation." (PMID 34662363, 2021). "Notably, when focusing on individual interactions of the cDCa cluster, MHC class II-related transcripts (eg, CD74, HLA-E) were predicted to interact with surface molecules such as MIF or KLRC1 with immunomodulatory capacity and known association to autoimmunity." (PMID 34783307, 2021). "Further study indicated that MIF could be released by secondary neutrophils from stores in the cytosol under conditions of insufficient clearance of apoptotic neutrophils in the sites of infection and autoimmunity." (PMID 31632367, 2019). "The MIF expression is individually variable in association with common genetic polymorphisms in MIF gene, including an SNP -173 G/C (rs7555622) and a microsatellite repeat sequence -794 CATT5-8 (rs5844572), which influences the clinical course of infectious diseases and risk of autoimmunity." (PMID 28646884, 2017). "However, we found that NS patients have elevated MIF plasma levels compared with control subjects, and these findings suggest MIF increased plasma levels might contribute to the autoimmunity on the one hand and to the epilepsy, brain damage and mental retardation on the other." (PMID 34662363, 2021).
Autoimmunity (continued). "Macrophages secrete the macrophage migration inhibitory factor (MIF) to enhance neutrophil survival and secretion of MMP-9, in the context of both cancer and autoimmunity." (PMID 26997761, 2016).
lung adenocarcinoma (24 papers, 2007 to 2025). A carcinoma that arises from the lung and is characterized by the presence of malignant glandular epithelial cells. "MIF overexpression in lung adenocarcinoma is associated with increased proliferation and migration and the development of multiple primary tumors." (PMID 38732068, 2024). "The macrophage migration inhibitory factor expression was positively associated with the occurrence of multiple primary lung adenocarcinomas." (PMID 37784249, 2023). "MIF and D-DT-deficient lung adenocarcinoma cells exhibit significantly less reduced glutathione levels and enhanced reactive oxygen species that were found to be necessary for the aberrantly activated AMPK observed in these cells." (PMID 24932684, 2014). "4-IPP dose-dependently inhibited lung adenocarcinoma clonogenic focus formation in a manner that closely resembles MIF/D-DT-deficiency." (PMID 24932684, 2014). "MIF gene overexpression was also recently identified as a component of a unique gene signature in lung adenocarcinoma, conferring a 53% 5-year recurrence-free survival for patients exhibiting the signature." (PMID 38732068, 2024). "When 4-IPP was developed as a more potent inhibitor of MIF compared to its prototypes, its efficacy was demonstrated by strongly inhibiting lung adenocarcinoma cell migration and proliferation." (PMID 38548753, 2024). "By differential expression analysis and LASSO logistic regression analysis we constructed an 8-gene (IKBKB, LTBR, MIF, PPARD, PPIA, PSME3, S100A6, SEMA4B) based risk score model to predict lymph node metastasis in lung adenocarcinoma." (PMID 34109216, 2021). "It has reported that MIF promotes cancer cell migration in human lung adenocarcinoma and esophageal squamous cell carcinoma." (PMID 32903462, 2020). "Combined, these data suggest that MIF and D-DT act in an additive and compensatory manner in promoting lung adenocarcinoma cell growth, division and survival." (PMID 24932684, 2014).
lung adenocarcinoma (continued). "Macrophage migration inhibitory factor (MIF) is an autocrine and paracrine acting cytokine/growth factor that promotes lung adenocarcinoma cell motility, anchorage-independence and neo-angiogenic potential." (PMID 24932684, 2014). "Lentiviral-delivered MIF and D-DT shRNA were introduced into A549 human lung adenocarcinoma cells, selected with puromycin, and then viable cells were plated and assessed for cell doubling by a simple cell counting assay." (PMID 24932684, 2014). "In human lung adenocarcinoma, MIF modulates tumor cell migration and invasion, in part by inducing the activation of the Rho GTPase Rac, and membrane lipid raft stabilization; features that are important in both driving and sustaining tumor cell invasion." (PMID 23522304, 2013). "BAFF-R expression in IgD+ CD24+ B cells was positively associated with lung adenocarcinoma (LUAD) risk (odds ratio [OR], 1.0168 [95% confidence interval [CI], 1.0006–1.0332]), mediated by macrophage migration inhibition factor (MIF) with a mediation proportion of 14.2% (95% CI, 0.00007–0.0046)." (PMID 41292522, 2025). "Importantly, functional cooperation by MIF and D-DT was found to extend to lung adenocarcinoma proliferative and clonal growth potential." (PMID 24932684, 2014). "Importantly, the functional overlap of MIF and D-DT in NSCLC pro-tumorigenic pathways provides strong rationale for the simultaneous therapeutic targeting of MIF and D-DT in lung adenocarcinoma malignant disease." (PMID 24932684, 2014). "Prior studies have reported that MIF is over-expressed in human lung adenocarcinomas." (PMID 23522304, 2013). "More recent studies demonstrate that MIF and D-DT additively antagonize the tumor suppressive activities of AMP-activated protein kinase (AMPK) in lung adenocarcinoma cells resulting in maximal mTOR pathway activation." (PMID 24932684, 2014). "The correlation between the expression of MIF and HIF-1α was validated in driver gene-negative lung adenocarcinoma patients, and the result revealed a significant positive correlation between the expression levels of MIF and HIF-1α in tumor tissues." (PMID 41210694, 2025). "Patients with driver gene-negative lung adenocarcinoma with high MIF expression had a poorer prognosis, and MIF expression levels were higher in patients with advanced disease." (PMID 41210694, 2025). "Pharmacological inhibition of MIF using the MIF irreversible inhibitor, 4-iodo-6-phenylpyrimidine (4-IPP) has shown a decrease in tumor aggressiveness in head and neck squamous cell carcinomas and lung adenocarcinomas." (PMID 26530123, 2015). "Meanwhile, single-cell sequencing was employed to conduct subpopulation analysis at the single-cell level in driver gene-negative lung adenocarcinoma, ultimately identifying MIF as a key gene involved in regulating glycolysis and playing a crucial role in regulating malignant cell transformation." (PMID 41210694, 2025). "We speculate that the presence of a MIF/HIF-1α positive feedback regulatory loop impacts the development of driver gene-negative lung adenocarcinoma through glycolysis mechanisms." (PMID 41210694, 2025). "Single-cell analysis of lung adenocarcinoma revealed that ACACA was expressed predominantly within malignant cells and contributed to an immunosuppressive microenvironment through migration inhibitory factor (MIF) signaling and the extracellular matrix (ECM) remodeling pathway." (PMID 41169354, 2025).